PTBP1 (polypyrimidine tract binding protein 1)
Diseases named in the same sentence as PTBP1 in open-access papers (continued):
Sharing a sentence is not in itself a finding about the gene and the disease.
liver cancer (16 papers, 2018 to 2025). An epithelial or non-epithelial malignant neoplasm that arises from the liver. "Moreover, the expression levels of PTBP1 were positively associated with the grades (Figure A2a) and metastasis status (Figure A2b) of liver cancer, suggesting a potentially oncogenic role of PTBP1 in liver cancer." (PMID 37724122, 2023). "This apparent contradiction regarding the role of PTBP1 in ferroptosis between EC and liver cancer highlights the critical importance of ​​cell type-specific context in determining RBP function." (PMID 41313521, 2025). "In contrast, in liver cancer cells under sorafenib treatment, PTBP1 promotes the translation of NCOA4 mRNA, a key regulator of ferritinophagy, which sensitizes cells to ferroptosis." (PMID 41313521, 2025). "In liver cancer, PTBP1 modulates ferroptosis through a mechanism involving nuclear receptor coactivator 4 (NCOA4)." (PMID 41313521, 2025). "In summary, these results indicated that PTBP1 positively regulates glutamine metabolism of liver cancer cells." (PMID 37724122, 2023). "Bioinformatics analysis showed that PTBP1 was markedly overexpressed in various cancers, including liver cancer (Figure A1)." (PMID 37724122, 2023). "In summary, our findings reveal tumorigenic roles for PTBP1 and the Axl-S isoform of Axl in liver cancer cell migration, invasion, and metastasis." (PMID 32483414, 2020). "We also identify PTBP1 as a key splicing regulator in controlling Axl pre-mRNA splicing, which plays an important role in mediating tumorigenesis of liver cancer cells." (PMID 32483414, 2020). "Our results also identified PTBP1 as an important splicing regulator that controls AS of Axl pre-mRNA, thereby promoting the invasion and metastasis of liver cancer cells." (PMID 32483414, 2020). "The effect of Axl-L, Axl-S, and PTBP1 on cell growth, migration, invasion tumor formation, and metastasis of liver cancer cells were measured by cell proliferation, wound-healing, invasion, xenograft tumor formation, and metastasis." (PMID 32483414, 2020). "Further studies demonstrated that PTBP1 and Axl-S are required for the process of liver cancer cell invasion and metastasis." (PMID 32483414, 2020). "The expression level of PTBP1 was positively correlated with the degree of liver cancer deterioration." (PMID 32483414, 2020). "As shown in, over-expression of PTBP1 in liver cancer cells significantly increased the expression of Axl-S while decreasing the expression of Axl-L." (PMID 32483414, 2020). "Both PTBP1 and Axl-S stimulate cell migration and invasion in vitro and promote tumorigenic and metastasis capacity of liver cancer cells in vivo." (PMID 32483414, 2020). "The degree of U2AF2 binding to Axl-minigene was significantly reduced in liver cancer cells knocked down by PTBP1." (PMID 32483414, 2020). "We screened the potential target genes of PTBP1 by RT-PCR, and the results showed that Axl is the main target gene of PTBP1 regulation in liver cancer cells." (PMID 32483414, 2020). "Overall, our results highlight the biological significance of the Axl-S isoform and PTBP1 in liver cancer invasion and metastasis." (PMID 32483414, 2020). "In-depth study of the PTBP1-Axl AS signal axis can provide new ideas for elucidating the metastasis mechanisms of liver cancer." (PMID 32483414, 2020). "We found that both PTBP1 and U2AF bind to Axl-minigene in liver cancer cells where PTBP1 is normally expressed." (PMID 32483414, 2020). "Consistent with expectations, we observed the opposite result in liver cancer cells knocked down by PTBP1." (PMID 32483414, 2020). "Interestingly, contrary to our conclusions, previous studies have shown that PTBP1 disruption in sorafenib-treated Huh-7 and HepG2 liver cancer cells significantly inhibits ferroptosis." (PMID 41313521, 2025). "In this study, the biological roles of PTBP1 in CDDP-resistant liver cancer were investigated." (PMID 37724122, 2023).
liver cancer (continued). "This study proposes that targeting the PTBP1–GLS–glutamine metabolism axis could be a potential strategy to overcome chemoresistance of liver cancer." (PMID 37724122, 2023). "The opposite phenomenon was observed in liver cancer cells over-expressing PTBP1." (PMID 32483414, 2020). "Noting the upregulation of Axl-S in high metastatic liver cancer cells with over-expressed PTBP1, we wondered whether the effect of PTBP1 on migration and invasion of liver cancer cell lines is Axl-S dependent." (PMID 32483414, 2020). "Moreover, PTBP1 was positively associated with CDDP resistance, indicating that PTBP1 is a potentially diagnostic biomarker and therapeutic target against chemoresistant liver cancer." (PMID 37724122, 2023). "Also, miR-194 inhibited key liver cancer phenotypes by modulating PTBP1/CCND3 signaling." (PMID 34716285, 2021). "After verification of the over-expression efficiency of Axl-L and Axl-S in liver cancer cells, we conducted a two-factor experiment of PTBP1 and Axl isoforms to investigate whether PTBP1 promotes liver cancer metastasis partially through regulating Axl-S levels." (PMID 32483414, 2020). "In addition, to test whether the absence of PTBP1 attenuated the percentage of Axl-S, we performed a knockdown of PTBP1 in liver cancer cells using shRNA." (PMID 32483414, 2020). "In conclusion, this study elucidates the tumorigenic roles of PTBP1 and the MAPT-L isoform of MAPT in liver cancer cell migration, invasion, and metastasis." (PMID 40296916, 2025). "The expression of PTBP1 in the highly metastatic liver cancer cell line HCCLM3 is significantly increased, and the expression level of PTBP1 in liver cancer tissues is significantly higher than that in normal tissues." (PMID 38002944, 2023). "We find that PTBP1 knockdown and MSI1 and PCBP2 overexpression are sufficient to activate many photoreceptor-specific exons in HepG2 liver cancer cells." (PMID 31919425, 2020). "Furthermore, the KIS interactome in liver cancer cells revealed a significant enrichment of potential KIS interactors in mRNA splicing, including hnRNPM and PTBP1." (PMID 38597390, 2024). "Knocking down of PTBP1 significantly blocked the protein expression of GLS, which catalyzes the speed-limiting reaction of glutamine metabolism in HCC cells and was significantly upregulated in liver cancer (Figure A4)." (PMID 37724122, 2023). "Overexpression of PTBP1 can significantly increase the migration and invasion of HCCLM3 cells, increase the expression of mesenchymal markers N-cadherin and vimentin, and promote the EMT process of liver cancer cells." (PMID 38002944, 2023). "The results of RT-PCR in showed that exon 10 skipping in minigene was significantly increased in liver cancer cells over-expressing PTBP1 compared with non-treated cells." (PMID 32483414, 2020). "After robust overexpression of MSI1 or PCBP2 (with or without simultaneous PTBP1 knockdown) in liver cancer cell lines, Ling and colleagues observed that MSI1 expression combined with downregulation of PTBP1 is linked to the activation of photoreceptor-specific exons." (PMID 38438733, 2024). "Validating the rationale of our screen, knockdown of PTBP1 suppresses the tumor-promoting effects of the SASP without reverting growth arrest in a preclinical model of advanced liver cancer, suggesting that SASP modulation can be a safe way to target inflammation-driven cancers." (PMID 29990503, 2018). "However, the precise roles and molecular targets of PTBP1 in regulating glutamine metabolism and CDDP resistance of liver cancer cells have not been elucidated." (PMID 37724122, 2023).
hepatocellular carcinoma (15 papers, 2020 to 2025). A malignant tumor that arises from hepatocytes. "PTBP1 has been detected to be an oncogene and associated with a range of cancers, including hepatocellular carcinoma." (PMID 36385098, 2022). "This study conducted an extensive investigation into the splicing factor PTBP1 and its subsequent AS landscape in hepatocellular carcinoma." (PMID 40296916, 2025). "In conclusion, through in vitro Transwell assays, in vivo xenograft, and in vivo imaging experiments, we concluded that PTBP1 partially promotes proliferation, invasion, and metastasis of hepatoma cells by regulating Axl-S levels." (PMID 32483414, 2020). "It was found that PTBP1 regulates lipid metabolism in hepatocellular carcinoma cells and thus inhibits oxidative stress and promotes hepatocellular carcinoma development by promoting the transport of the key gene for fatty acid synthesis, FASN mRNA, into the cytoplasm to facilitate its translation." (PMID 40579921, 2025). "In hepatocellular carcinoma, PTBP1 could promote cisplatin resistance via strengthening glutamine uptake and enhancing glutaminase (GLS) expression." (PMID 38993556, 2024). "Furthermore, SNHG6 can interact with heterogeneous nuclear ribonucleoprotein L (HNRNPL) and polypyrimidine tract binding protein 1 (PTBP1) to promote the progression of hepatocellular carcinoma." (PMID 37004005, 2023). "Furthermore, PTBP1 is also involved in redox homeostasis in hepatocellular carcinoma cells." (PMID 40579921, 2025). "PTBP1 converts oncogenic FGFR2‐IIIb to pro‐carcinogenic FGFR2‐IIIc isoforms by modulating the selective splicing of FGFR2, which ultimately promotes hepatocellular carcinoma development." (PMID 40579921, 2025). "In hepatocellular carcinoma, miR‐194 inhibits PTBP1 expression by binding to the 3′‐UTR of PTBP1 mRNA, leading to a decrease in cell cycle protein D3 (CCND3) protein levels, which affects the cell cycle and tumour progression." (PMID 40579921, 2025). "In addition, polypyrimidine pathway binding protein 1 (PTBP1) has been shown to mediate ferroptosis in hepatocellular carcinoma cells by regulating the translation of NCOA4, and the PTBP1-NCOA4 axis may be an important pathway for ferritinophagy-mediated ferroptosis." (PMID 38834843, 2024). "The MALAT1-stabilized PTBP1/PSF interaction occurs in multiple cellular contexts; however, the functional module, relative to MALAT1 only, has more dominant pathological significance in hepatocellular carcinoma." (PMID 36563164, 2022).
neuroblastoma (11 papers, 2011 to 2024). Neuroblastoma (NB) is the most common solid, extracranial childhood tumor. "This is because the PKM2 isoform is enriched in MYCN-amplified neuroblastoma cells due to the ability of the MYC transcription factors to transactivate the splicing factors PTBP1 and HNRNPA." (PMID 34847775, 2021). "The PKM2 splicing switch and PTBP1 expression upregulation we found in stage 4+ neuroblastoma suggest a MYCN-controlled pathway for PKM2 splicing in neuroblastoma." (PMID 21501490, 2011). "Interestingly, hnRNPA1 was previously demonstrated to be a MYCN target gene mediating AS in neuroblastoma, and a comparison of our DSGs with DSGs reported in RNAseq of hnRNPA1/PTBP1 knockdowns demonstrated a significant overlap." (PMID 39313128, 2024).
ovarian carcinoma (11 papers, 2014 to 2024). A malignant neoplasm originating from the surface ovarian epithelium. "Our previous study showed that PTBP1 was overexpressed in human ovarian tumors and a panel of ovarian cancer cell lines." (PMID 26336992, 2015). "Polypyrimidine tract binding protein (PTB/PTBP1) is overexpressed in ovarian cancer and gliomas, and has been shown to promote invasive behavior through splicing pattern changes in genes related to cell migration." (PMID 25908786, 2015). "We used one previously reported single paired RNA-Seq sample as well as our new datasets derived from breast and ovarian cancer cell lines, and PTBP1-depleted and matched control samples." (PMID 25079003, 2014). "In conclusion, our study confirms the important role of TPTEP1 in ovarian cancer (OC) progression and suggests that TPTEP1 inhibits the PI3K/AKT signalling pathway by directly binding PTBP1, possibly indicating the molecular mechanism underlying its biological function." (PMID 39422584, 2024). "Interestingly, a recent report showed that downregulation of PTBP1 sensitizes ovarian cancer cells to chemotherapeutic agents such as carboplatin or paclitaxel." (PMID 24743263, 2014).
pancreatic cancer (11 papers, 2011 to 2025). "In pancreatic cancer cells, linc‐ROR regulation of the miR‐124/PTBP1/PKM2 axis of action resulted in gemcitabine resistance in pancreatic cancer cells." (PMID 40579921, 2025). "In studies on pancreatic cancers, PTBP1 has been shown to regulate the spicing of the pyruvate kinase (PKM) mRNA and thereby resulting in gemcitabine resistance." (PMID 31729427, 2019). "It is revealing that the depletion of RBMX, EWS, FUS, SKIP and Tra2 all augment DNA damage-induced apoptosis, and that knocking down PTBP1 abolishes resistance to genotoxic drugs in pancreatic cancer cells." (PMID 26529031, 2015). "Additionally, PTBP1 was demonstrated to alter the alternative splicing process of PKM to promote gemcitabine resistance in pancreatic cancer cells." (PMID 31355266, 2019). "In pancreatic cancer, linc-ROR confers gemcitabine resistance at least partly via inducing autophagy, and further research reported a linc-ROR/miR-124/PTBP1/PKM2 axis that involved in the regulation of gemcitabine resistance in pancreatic cancer cells." (PMID 30266744, 2018). "In two studies, the splicing factors PTBP1 and TRA2A were up-regulated in resistant cells and promoted resistance to gemcitabine in pancreatic cancer through AS regulation of the PKM gene, and to paclitaxel in triple-negative breast cancer through AS of RSRC2, respectively." (PMID 31943118, 2020).
Parkinson disease (11 papers, 2018 to 2025). A progressive degenerative disorder of the central nervous system characterized by loss of dopamine producing neurons in the substantia nigra and the presence of Lewy bodies in the substantia nigra and locus coeruleus. "Meanwhile, prior research on the protective effect of Ptbp1 knockdown in neural injuries and neurodegenerative disorders, such as Parkinson's disease and optic nerve injury, has predominantly centered on the brain." (PMID 40702752, 2025). "Recent studies show that targeting PTBP1 by ASOs can convert midbrain ACs to dopaminergic neurons and improved Parkinson’s disease in mice, and that PTBP1 knockdown promotes neuronal-like differentiation of IDH-WT GBM cell lines." (PMID 38662454, 2024). "In Parkinson’s disease mouse models, direct reprogramming astrocytes into dopaminergic neurons through depleting Ptbp1 improves Parkinson’s disease-like motor phenotypes." (PMID 33924833, 2021). "In vivo Ptbp1 knockdown has recently been reported to directly convert astrocytes in the striatum or substantia nigra into dopaminergic neurons, which reverses motor neuron dysfunction in chemically induced Parkinson’s disease model mice." (PMID 34068607, 2021). "PTBP1 (down), in parallel with HNF4A (up), was identified as the most significant blood biomarkers in Parkinson’s Disease through transcriptomic and network-based meta-analysis." (PMID 29936497, 2018).
acute myeloid leukemia (10 papers, 2020 to 2026). Acute myeloid leukemia (AML) is a group of neoplasms arising from precursor cells committed to the myeloid cell-line differentiation. "LncRNA SNHG5 stabilized autophagy related 5 (ATG5) mRNA and induced cancer-associated fibroblasts-like phenotype by interaction with PTBP1 in acute myeloid leukemia cells." (PMID 40790019, 2025). "For example, circ-MYBL2, a circRNA from MYBL2 gene, is reported to facilitate the progression of acute myeloid leukemia by regulating fms-related receptor tyrosine kinase 3 (FLT3) translation through recruiting polypyrimidine tract binding protein 1 (PTBP1)." (PMID 38165465, 2024). "circMYBL2 has been reported to regulate FMS-like tyrosine kinase-3 (FLT3) translation by recruiting polypyrimidine tract-binding protein 1 (PTBP1) to promote FLT3-internal tandem duplication in acute myeloid leukemia progression." (PMID 34322012, 2021). "In addition, circMYBL2 (derived from the cell cycle checkpoint gene MYBL2) facilitates protein translation and exacerbates acute myeloid leukemia by enhancing the interaction between polypyrimidine tract-binding protein 1 (PTBP1) and FMS-like tyrosine kinase 3 (FLT3) mRNA." (PMID 39062737, 2024). "In acute myeloid leukemia (AML), SNHG5 interacts with PTBP1, stabilizing ATG5 mRNA and inducing autophagy in mesenchymal stromal cells (MSCs), which in turn acquire a cancer-associated fibroblast (CAF)-like phenotype, ultimately enhancing chemoresistance." (PMID 41550840, 2026). "In acute myeloid leukemia (AML), the circMYBL2 (hsa_circ_0006332) could directly bind to Polypyrimidine Tract Binding Protein 1 (PTBP1), leading to AML progression and quizartinib resistance." (PMID 35205613, 2022).